ZNF37BP (zinc finger protein 37B, pseudogene)
Synonyms: KOX21; FLJ23327; formerly ZNF37B
Gene: Transcribed processed pseudogene on chromosome 10 (42,519,695 to 42,521,046, reverse strand). Ensembl gene ENSG00000234420.
Diseases named in the same sentence as ZNF37BP in open-access papers:
ZNF37BP is named in the same sentence as 2 diseases in open-access papers, as found by Europe PMC text mining. Sharing a sentence is not in itself a finding about the gene and the disease.
ZNF37BP shares sentences with these, for which no sentence is quoted: cancer (1 paper); osteosarcoma (1).